MIR548X (microRNA 548x)
Synonyms: hsa-mir-548x
Gene: MicroRNA gene on chromosome 21 (18,686,090 to 18,686,164, reverse strand). Ensembl gene ENSG00000265841.
Homologues: Orthologues: chimpanzee MIR548X (100% identical). Paralogues in human: MIR548AZ (84% identical), MIR548P (84% identical), MIR548F1 (81% identical), MIR548F3 (81% identical), MIR548K (80% identical), MIR548H3 (79% identical), MIR548X2 (77% identical), MIR548AA1 (76% identical), MIR548N (76% identical), MIR548AH (75% identical), MIR548AJ1 (75% identical), MIR548AN (75% identical), and 13 more.
Diseases named in the same sentence as MIR548X in open-access papers:
MIR548X is named in the same sentence as 2 diseases in open-access papers, as found by Europe PMC text mining. Sharing a sentence is not in itself a finding about the gene and the disease.
MIR548X shares sentences with these, for which no sentence is quoted: adenoma (1 paper); cancer (1).